LIMK1 (LIM domain kinase 1)
Diseases named in the same sentence as LIMK1 in open-access papers (continued):
Sharing a sentence is not in itself a finding about the gene and the disease.
osteosarcoma (10 papers, 2015 to 2023). A usually aggressive malignant bone-forming mesenchymal neoplasm, predominantly affecting adolescents and young adults. "In these conditions, LIMK1 phosphorylation is reduced, indicating a possible role for LIMK1 in regulating the osteosarcoma cell proliferation via the insulin/PI3K/LIMK1 signalling pathway." (PMID 36899941, 2023). "Insulin promotes the proliferation of MG63 osteosarcoma cells in a time- and dose-dependent manner, and also induces LIMK1 and cofilin phosphorylation." (PMID 36899941, 2023). "6-hydroxythiobinupharidine that was isolated from Nuphar pumilum also suppressed the migration of murine LM8 osteosarcoma cells by decreasing the expression of LIMK1 and cofilin phosphorylation." (PMID 36899941, 2023). "Several studies have shown that LIMK1 is overexpressed in osteosarcoma through immunohistochemistry on patient tissues." (PMID 36899941, 2023). "Studies have shown that high expression of LIMK1 can promote invasion and metastasis of osteosarcoma cells resistant to vincristine." (PMID 35265128, 2022). "The migration of osteosarcoma cells decreased after LIMK1 silencing." (PMID 35265128, 2022). "Overexpression of LIMK1 promotes the migration of multidrug-resistant osteosarcoma cells." (PMID 30873211, 2019). "The knockdown of LIMK1 inhibited the migration of MG63/VCR cells, suggesting that LIMK1 dysregulation contributes to the invasion and metastasis potential of drug-resistant osteosarcoma." (PMID 36899941, 2023).
glioma (9 papers, 2014 to 2024). A benign or malignant brain and spinal cord tumor that arises from glial cells (astrocytes, oligodendrocytes, ependymal cells). "Major TGF-Beta-EMT inducing factors (RHOA, RAC1, ROCK2, CDC43 and LIMK1) and EMT transcription factors (TWIST1, SOX9, TRIM28 and SERP2) have among the highest risk scores in our glioma transcriptional model." (PMID 28916782, 2017). "Based on gene expression, glioma patients (grades II–IV) with downregulated LIMK1 and LIMK2 had significantly better overall survival (p>0.05)." (PMID 25237832, 2014). "In summary, LIMK1 and LIMK2 down-regulation correlates with better overall survival in glioma patients; and DNA copy number gains of LIMK1 correlate with worse survival in GBM patients." (PMID 25237832, 2014).
colon carcinoma (8 papers, 2012 to 2023). "The Kaplan–Meier survival curve analysis showed that the expression of LIMK1 and destrin was closely associated with the overall survival (OS) of colon cancer." (PMID 28358024, 2017). "This study reported that LIMK1 and destrin were highly expressed in colon cancer and associated with poor prognosis of patients with colon cancer." (PMID 28358024, 2017). "LIMK1 is highly expressed by colon cancer tissues, and inhibiting the expression of LIMK1 can reduce the proliferation, invasion and epithelial–mesenchymal transition of colon cancer cells by interacting with STK25." (PMID 36836593, 2023). "The results of this study showed that knockdown of LIMK1 inhibited the proliferation of colon cancer cells." (PMID 35265128, 2022). "Fluorescence quantitative PCR and immunohistochemistry were used to detect the expression of the LIMK1 gene in cancer and adjacent tissues of 20 clinical colon cancer samples." (PMID 35265128, 2022). "The limitation of this study is that the specific molecular mechanism of the LIMK1 gene in the occurrence and development of colon cancer is still unclear." (PMID 35265128, 2022). "Further in vivo studies showed that colon cancer cells with LIMK1 knockdown grew slower in a nude mouse model of colon cancer." (PMID 35265128, 2022). "Coexpression correlation analysis results showed that in colon cancer tissues, the coexpression of LIMK1 was positively correlated with EMT marker Vimentin." (PMID 35265128, 2022). "Real-time quantitative PCR results showed that the expression of LIMK1 in 20 colon cancer tissues was higher than that in adjacent tissues." (PMID 35265128, 2022). "Immunohistochemical results showed that the positive rate of LIMK1 in colon cancer tissues was higher than that in para-cancer tissues." (PMID 35265128, 2022). "TCGA database analysis results showed that the expression of LIMK1 was also related to the staging and metastasis of colon cancer patients." (PMID 35265128, 2022). "Meanwhile, the results of the growth curve showed that the growth rate of colon cancer cells was significantly reduced after LIMK1 gene silencing compared with the control group (P < 0.01)." (PMID 35265128, 2022). "In order to study the role of LIMK1, the correlation between LIMK1 expression level and prognosis of colon cancer patients was analyzed by using TCGA data." (PMID 35265128, 2022). "DADS reduced cancer cell invasion and migration by decreasing the phosphorylation of ADF/cofilin via the suppression of LIMK1 in colon cancer cells." (PMID 36071845, 2022). "In vitro experiments demonstrated that the overexpression of LIMK1 significantly promoted the proliferation of colon cancer cells, and DADS significantly inhibited the proliferation of colon cancer cells and arrested the cell cycle in the G2/M phase." (PMID 28358024, 2017). "The expression of LIMK1 and destrin was analyzed using the immunohistochemical staining of the colon cancer tissue array to evaluate the relationship between the expression of LIMK1 and destrin and colon cancer." (PMID 28358024, 2017). "It indicated that the poorer the differentiation of colon cancer, the higher the expression of LIMK1 and destrin." (PMID 28358024, 2017). "The results showed that the upregulation of LIMK1 promoted colon cancer cell proliferation, invasion, and migration." (PMID 28358024, 2017). "The scratch wound-healing assay showed that compared with the untreated and empty vector groups, the overexpression of LIMK1 in colon cancer cells led to faster wound healing, and cell migration was significantly enhanced." (PMID 28358024, 2017). "The results further illustrated that the expression of LIMK1 and destrin promoted the development of colon cancer, and the high expression of LIMK1 and destrin was a potential molecular marker for poor prognostic monitoring in colon cancer." (PMID 28358024, 2017).
colon carcinoma (continued). "After DADS treatment or silencing the expression of LIMK1, the expression of E-cadherin significantly increased in colon cancer cells, whereas the overexpression of LIMK1 significantly reduced the expression of E-cadherin." (PMID 28358024, 2017). "The present results suggested that the significantly high expression of LIMK1 and destrin was related to the occurrence and development of colon cancer." (PMID 28358024, 2017). "The reduction in the expression of LIMK1 had a synergistic effect with DADS treatment for inhibiting human colon cancer cell invasion and migration." (PMID 28358024, 2017). "The present study further confirmed that the expression and phosphorylation levels of LIMK1 significantly increased during colon cancer cell invasion and migration." (PMID 28358024, 2017). "DADS inhibited the phosphorylation of ADF/cofilin by downregulating the expression of LIMK1, thereby inhibiting colon cancer migration and invasion." (PMID 28358024, 2017). "DADS obviously inhibited migration and invasion by suppressing the phosphorylation of ADF/cofilin via downregulation of LIMK1 in colon cancer cells." (PMID 28358024, 2017). "A colon cancer cell line with the stable expression of LIMK1was established in the present study to further clarify the role of LIMK1 in DADS-mediated inhibitory effect on colon cancer cell proliferation, migration, and invasion." (PMID 28358024, 2017). "The results suggested that the overexpression of LIMK1 and destrin promoted the progression and metastasis of colon cancer." (PMID 28358024, 2017). "Compared with intestinal epithelial hiEC-6, LIMK1 is highly expressed in colon cancer cell lines." (PMID 35265128, 2022). "However, the expression of LIMK1 in colon cancer and its molecular mechanism on the proliferation and migration of colon cancer cells remain to be further studied." (PMID 35265128, 2022). "In this study, LIMK1 can interact with STK25 to promote the EMT process in colon cancer." (PMID 35265128, 2022). "The overexpression of LIMK1 considerably aids colon cancer cell invasion and migration." (PMID 36071845, 2022). "An shRNA specific to LIMK1 was synthesized and transfected into colon cancer cell lines." (PMID 35265128, 2022). "High expression of LIMK1 and STK25 is associated with poor prognosis in colon cancer patients." (PMID 35265128, 2022). "Furthermore, DADS was shown to inhibit colon cancer cell proliferation, migration, and invasion owing to the negative regulation of LIMK1–ADF/cofilin signaling pathway." (PMID 28358024, 2017). "Moreover, the expression of LIMK1 was positively correlated with the expression of destrin (r = 0.487, P < 0.001) in colon cancer." (PMID 28358024, 2017). "The overexpression of LIMK1 significantly promoted colon cancer cell migration and invasion." (PMID 28358024, 2017). "It was found previously that DADS could downregulate the expression and phosphorylation of LIMK1 in SW480 colon cancer cells." (PMID 28358024, 2017). "This study examined whether the overexpression of LIMK1 could antagonize the inhibitory effect of DADS on colon cancer cell migration and invasion to further define the role of LIMK1 gene in the inhibitory effect of DADS on cancer cell migration and invasion." (PMID 28358024, 2017). "The expression of LIMK1 protein was positively correlated with the expression of destrin, suggesting that LIMK1 and destrin might contribute to carcinogenesis and the clinical progression of colon cancer." (PMID 28358024, 2017). "The relationship between the expression of LIMK1 and destrin and clinicopathological parameters and prognosis was analyzed to clarify the clinical significance of the expression of LIMK1 and destrin, and the role of prognostic monitoring in colon cancer." (PMID 28358024, 2017). "Silencing the expression of LIMK1 may enhance the inhibitory effect of DADS on colon cancer cell migration and invasion." (PMID 28358024, 2017).
colon carcinoma (continued). "After DADS (45 mg/L) treatment, colon cancer cell migration could be significantly reduced, but the overexpression of LIMK1 could weaken such inhibition by DADS." (PMID 28358024, 2017). "The present study investigated whether DADS could downregulate LIMK1 in colon cancer cells with the overexpression of LIMK1, inhibiting the expression of ADF/cofilin." (PMID 28358024, 2017). "It was found that after DADS treatment in colon cancer cells, the expression of destrin mRNA and protein was significantly suppressed, while the overexpression of LIMK1 significantly upregulated the expression of destrin and weakened the inhibition of the expression of destrin by DADS." (PMID 28358024, 2017). "Previous studies have shown that silencing LIMK1 could significantly enhance the inhibitory effect of DADS on colon cancer cell migration and invasion, suggesting that LIMK1 was a target molecule of DADS, which needed further confirmation." (PMID 28358024, 2017). "Hence, LIMK1 and destrin might serve as potential molecular markers for poor prognostic monitoring in colon cancer." (PMID 28358024, 2017). "Also, silencing the expression of LIMK1 might enhance the inhibitory effect of DADS on colon cancer cell migration and invasion." (PMID 28358024, 2017). "Also, patients with colon cancer having a low expression of LIMK1 and destrin had a significantly longer OS compared with the patients having high expression [80.469 ± 5.629 vs 43.322 ± 2.665, hazard ratio (HR) = 3.084, P = 0.007; 80.824 ± 5.847 vs 56.335 ± 4.304,HR = 2.617, P = 0.033]." (PMID 28358024, 2017). "Also, DADS could inhibit colon cancer growth, invasion, and migration by downregulating the expression of LIMK1." (PMID 28358024, 2017). "Thus, both in vitro and in vivo results showed that the upregulation of LIMK1 promoted colon cancer cell growth, and DADS could inhibit colon cancer growth by downregulating the expression of LIMK1." (PMID 28358024, 2017). "LIMK1 can mediate the proliferation, invasion, migration, and EMT of colon cancer cells through its interaction with STK25." (PMID 35265128, 2022). "Overexpression of LIMK1 and STK25 plays a role in promoting cell proliferation and invasion in colon cancer tissues and cells." (PMID 35265128, 2022). "The overexpressed plasmid group cotransfected with LIMK1 and STK25 showed the strongest proliferation and invasion ability of colon cancer cells." (PMID 35265128, 2022). "The effects of LIMK1 and STK25 on the proliferation and invasion of colon cancer cell lines were detected by CCK-8 assay, Transwell, and clonogenesis." (PMID 35265128, 2022). "SW620 cells were selected to study the effect of the LIMK1 gene on proliferation and EMT in colon cancer cells." (PMID 35265128, 2022). "This study provides a new understanding of the mechanism of LIMK1 leading to proliferation, invasion, migration, and EMT of colon cancer cells." (PMID 35265128, 2022). "The present study found that LIMK1 and destrin (also known as ADF) were highly expressed in colon cancer." (PMID 28358024, 2017). "The overexpression of LIMK1 significantly accelerated the phosphorylation of ADF/cofilin, hence promoting colon cancer cell migration and invasion." (PMID 28358024, 2017). "In summary, the present study showed that LIMK1 and destrin (ADF) were highly expressed in colon cancer tissue, and the overexpression of LIMK1 significantly promotedcolon cancer cell migration and invasion." (PMID 28358024, 2017). "DADS can downregulate the expression of LIMK1 to inhibit the LIMK1–ADF/cofilin signaling pathway, and impede angiogenesis and EMT, thereby inhibiting the migration and invasion of colon cancer." (PMID 28358024, 2017). "This study analyzed the expression and biological role of LIMK1 and STK25 in colon cancer." (PMID 35265128, 2022). "It was further confirmed that reduced LIMK1 expression could inhibit the proliferation and EMT of colon cancer cells." (PMID 35265128, 2022).
colon carcinoma (continued). "The effect of LIMK1 and STK25 on the malignant progression of colon cancer was analyzed." (PMID 35265128, 2022). "LIMK1 interacted with STK25 and was highly expressed in colon cancer." (PMID 35265128, 2022). "Cotransfection of LIMK1 and STK25 promotes the malignant progression and EMT of colon cancer." (PMID 35265128, 2022). "Our previous study found that RAC1 could significantly induce the EMT of colon cancer cells, which may be related to the positive regulation of Rac1/PAK1/LIMK1/Cofilins signaling pathway." (PMID 32411607, 2020). "This study aimed to explore whether the downregulation of LIM kinase 1 (LIMK1)-actin depolymerization factor (ADF, also known as destrin)/cofilin by diallyl disulfide (DADS) inhibited the migration and invasion of colon cancer." (PMID 28358024, 2017). "Subsequently, the study explored the effects of DADS on the LIMK1–ADF/cofilin signaling pathway, focusing on whether the downregulation of LIMK1 was related to the DADS-induced inhibition of the migration and invasion of colon cancer." (PMID 28358024, 2017). "The present study confirmed that LIMK1 and destrin (ADF) were overexpressed in primary colon cancer, which was correlated with the pathological grade, tumor size, clinical stage, lymph node metastasis, and poor prognosis of colon cancer." (PMID 28358024, 2017). "DADS could significantly decrease the expression of LIMK1 and destrin in SW480 human colon cancer cells." (PMID 28358024, 2017). "The LIMK1 and STK25 pathways may be new therapeutic targets for colon cancer." (PMID 35265128, 2022). "Thus, it was speculated that LIMK1 might be a key target molecule for the inhibitory effect of DADS on cell migration and invasion of human colon cancer, which needed further confirmation." (PMID 28358024, 2017). "Interestingly, LIMK1/2 are also downstream effectors of p21-activated kinases (PAK), which, as we have previously shown regulate formation of the fascin-1/cPKC complex in colon carcinoma cells, and which also correlate clinically with metastatic progression." (PMID 22883572, 2012). "The expression of LIMK1 and destrin was related to the pathological degree of differentiation (P = 0.001, P = 0.022), tumor size (P = 0.001, P = 0.004), clinical stage (P = 0.002, P = 0.007), and metastasis (P < 0.001, P = 0.009) in colon cancer, but not to gender and age." (PMID 28358024, 2017).
Alzheimer disease (7 papers, 2014 to 2025). A progressive, neurodegenerative disease characterized by loss of function and death of nerve cells in several areas of the brain leading to loss of cognitive function such as memory and language. "The increased activity of the LIMK1 isoform has been associated with several diseases including Alzheimer’s diseases (AD), cancer, and HIV." (PMID 34966720, 2021). "A Mapt mutation is associated with neurodegenerative disorders such as Alzheimer disease, while the brain-specific Limk1 is implicated in axonal elongation." (PMID 25299227, 2014).
epilepsy (7 papers, 2017 to 2025). A brain disorder characterized by episodes of abnormally increased neuronal discharge resulting in transient episodes of sensory or motor neurological dysfunction, or psychic dysfunction. "Individual 1 showed developmental delay and epilepsy, and decreased actin polymerization in patient-derived fibroblasts suggested decreased LIMK1 kinase activity." (PMID 40491492, 2025). "In the intra-amygdala kainate model of epilepsy in mice, the upregulation of miR-134 expression was followed by a corresponding decrease of transcript levels of Limk1 and Creb1 in the hippocampus." (PMID 36240080, 2022). "Epilepsy develops in part from the increase in LIMK1 translation decrease." (PMID 40530256, 2025). "In pediatric patients with epilepsy, miR-27a-3p plasma levels were also lower than in healthy children as reported in adult patients; miR-27a-3p reduced the levels of Limk1, suggesting that Limk1 is a target of miR-27a-3p." (PMID 38525737, 2024). "While LIMK1 knockout mice show disrupted neurotransmitter exocytosis, they do not present with epilepsy." (PMID 40491492, 2025).